ENSG00000202275
Synonyms: LOC124900347
Gene: Small nucleolar RNA gene on chromosome 14 (103,797,272 to 103,797,348, reverse strand). Ensembl gene ENSG00000202275.
Gene Ontology:
Biological process: RNA processing
Cellular component: nucleolus
Homologues: Paralogues in human: SNORD51 (83% identical).